DGCR2 (DiGeorge syndrome critical region gene 2)
Description:
Putative adhesion receptor, that could be involved in cell-cell or cell-matrix interactions required for normal cell differentiation and migration.
Synonyms: IDD; KIAA0163; LAN; DGS-C; SEZ-12
Tractability: Antibody: UniProt predicts a signal peptide or a membrane-spanning region. PROTAC: ubiquitination databases record sites on it.
Gene: Protein-coding gene on chromosome 22 (19,036,280 to 19,122,461, reverse strand). Ensembl gene ENSG00000070413.
Subcellular location: Membrane
Gene Ontology:
Molecular function: protein binding
Biological process: cognition; animal organ morphogenesis
Cellular component: membrane
Genetic constraint (gnomAD): Loss-of-function variants: 24 observed, 49.19 expected, observed/expected ratio (o/e) 0.49, 90% interval 0.35 to 0.69. The upper end of that interval is the gene's LOEUF score, 0.69, which puts it in group 2 of 6, group 1 being the genes least tolerant of losing a copy. Missense variants: 765 observed, 776.12 expected, observed/expected ratio (o/e) 0.99, 90% interval 0.93 to 1.05. Synonymous variants: 340 observed, 316.28 expected, observed/expected ratio (o/e) 1.08, 90% interval 0.98 to 1.18.
Homologues: Orthologues: chimpanzee DGCR2 (99% identical), macaque DGCR2 (98% identical), mouse Dgcr2 (93% identical), guinea pig DGCR2 (92% identical), pig DGCR2 (89% identical), dog DGCR2 (88% identical), rat Dgcr2 (87% identical), rabbit DGCR2 (82% identical), tropical clawed frog dgcr2 (74% identical), zebrafish dgcr2 (64% identical), Drosophila melanogaster CG32647 (13% identical).
Diseases named in the same sentence as DGCR2 in open-access papers:
DGCR2 is named in the same sentence as 10 diseases in open-access papers, as found by Europe PMC text mining. Sharing a sentence is not in itself a finding about the gene and the disease. The quoted sentences say what the papers report.
schizophrenia (6 papers, 2008 to 2023). A major psychotic disorder characterized by abnormalities in the perception or expression of reality. "DGCR2 is one of the deleted genes within 22q11.2 deletion, which is a strongest genetic risk factor for schizophrenia." (PMID 37480133, 2023). "An Ashkenazi Jewish population study has found that several single nucleotide polymorphisms (SNPs) within DGCR2 are associated with schizophrenia, and the risk allele of one SNP has a reduced expression level in the brain." (PMID 37480133, 2023). "DiGeorge syndrome critical region gene 2 (DGCR2) is one of the deleted genes among the critical region and is also associated with schizophrenia." (PMID 37480133, 2023). "DiGeorge syndrome critical region gene 2 (DGCR2) is one of the deleted genes within the 22q11.2 deletion syndrome (22q11DS), which is a high risk for developing schizophrenia." (PMID 37480133, 2023). "Here we provide evidence that the expression of DGCR2, a schizophrenia risk gene, increased during neurodevelopmental stages and was enriched in the PSDs." (PMID 37480133, 2023). "DGCR2 is associated with susceptibility to schizophrenia, and is expressed throughout brain development." (PMID 36468003, 2022). "An exome sequencing study found that a de novo mutation in DGCR2 is associated with schizophrenia." (PMID 37480133, 2023). "In the same direction association studies have reported several genes of this region associated with risk to develop schizophrenia and bipolar disorder, including PRODH, COMT, ZNF74, PCQAP, UFD1L, ZDHHC8, DGCR2 and SNAP29." (PMID 18284679, 2008). "However, the pathophysiological mechanism of DGCR2 in schizophrenia or 22q11DS is still unclear." (PMID 37480133, 2023).
22q11.2 deletion syndrome (5 papers, 2016 to 2023). 22q11.2 deletion syndrome (DS) is a chromosomal anomaly which causes a congenital malformation disorder whose common features include cardiac defects, palatal anomalies, facial dysmorphism, developmental delay and immune deficiency. "Our results suggest that Dgcr2 plays a role in motor control related to Purkinje cell function and that the deficiency of DGCR2 contributes at least to some of the symptoms of patients of 22q11.2 deletion syndrome." (PMID 28955813, 2016). "The exact function of DGCR2 is unknown, but the deletion of the associated gene causes 22q11.2DS (previously known as DiGeorge syndrome), a developmental disorder." (PMID 38100042, 2023). "CTLDs were classified to seventeen groups; Hc-clec-160 was similar to the group XIII DGCR2 (DGCR2/ DD/ Sez 12), which is localized in the DiGeorge syndrome (OMIM 188400) critical region." (PMID 30029661, 2018). "It has been suggested that the DGCR2 gene plays a role in the pathogenesis of 22q11.2 deletion syndrome." (PMID 28955813, 2016). "DGCR2, DGCR8, and UFD1 are deleted in individuals with 22q11.2 deletion syndrome (22q11DS), which occurs in individuals who have increased susceptibility for psychiatric disorders." (PMID 30923314, 2019).
mental disorder (2 papers, 2019 to 2023). A disease that has its basis in the disruption of mental process. "Our findings provide mechanistic insight into the pathophysiological roles of DGCR2 in 22q11DS and related mental disorders." (PMID 37480133, 2023). "This study provides a potential pathophysiological mechanism of DGCR2 in 22q11DS and related mental disorders." (PMID 37480133, 2023). "Overall, our study provides a potential pathophysiological mechanism of DGCR2 in 22q11DS and related mental disorders." (PMID 37480133, 2023). "Together, these results demonstrate that DGCR2 plays a critical role in regulating dendritic spine development, thus revealing potential pathophysiological mechanisms of 22q11DS and related mental disorders." (PMID 37480133, 2023).
Anxiety (1 paper, 2023). Intense feelings of nervousness, tension, or panic often arise in response to interpersonal stresses. "Consequently, abnormal behaviors, like anxiety, were observed in DGCR2-deficient mice." (PMID 37480133, 2023).
autism spectrum disorder (1 paper, 2023). A spectrum of developmental disorders that includes autism, and Asperger syndrome. "For autism spectrum disorder, DGCR2, ARVCF, GNB1L, COMT, ZDHHC8, CHRNA7, and NRXN1 are candidate genes with various associated developmental defects." (PMID 37486921, 2023).
thymic hypoplasia (1 paper, 2021). "Haploinsufficiency of the distally located HDR1 region is associated with hypoparathyroidism, deafness and renal anomalies, whereas deletion of the more proximal DGCR2 is associated with CHD and thymic hypoplasia." (PMID 33257998, 2021). "One DGCR2-located gene, CELF2 (previously called BRUNOL3), is a premRNA alternative splicing factor that is strongly expressed in the developing thymus and has been proposed as a candidate gene for thymic hypoplasia." (PMID 33257998, 2021).
DGCR2 also shares sentences with these, for which no sentence is quoted: bipolar disorder (1 paper); dementia (1); Hypocalcemia (1); Tremor (1).